SFTPD (surfactant protein D)
Description:
Contributes to the lung's defense against inhaled microorganisms, organic antigens and toxins. Interacts with compounds such as bacterial lipopolysaccharides, oligosaccharides and fatty acids and modulates leukocyte action in immune response. May participate in the extracellular reorganization or turnover of pulmonary surfactant. Binds strongly maltose residues and to a lesser extent other alpha-glucosyl moieties.
Synonyms: PSP-D; SP-D; COLEC7; SFTP4
Tractability: Small molecule: a structure with a bound ligand is known; it has a high-quality binding pocket. Antibody: its Gene Ontology location is reachable by antibodies, with high confidence; UniProt places it where antibodies can reach, with medium confidence; UniProt predicts a signal peptide or a membrane-spanning region.
Gene: Protein-coding gene on chromosome 10 (79,937,128 to 79,983,996, reverse strand). Ensembl gene ENSG00000133661.
Subcellular location: Secreted, extracellular space, extracellular matrix; Secreted, extracellular space, surface film
Pathways (Reactome):
Disease: Defective CSF2RA causes SMDP4; Defective CSF2RB causes SMDP5; SARS-CoV-1 activates/modulates innate immune responses; SARS-CoV-2 activates/modulates innate and adaptive immune responses
Immune System: Immunoregulatory interactions between a Lymphoid and a non-Lymphoid cell; Regulation of TLR by endogenous ligand; Toll Like Receptor 4 (TLR4) Cascade; Toll Like Receptor TLR1:TLR2 Cascade
Cell-Cell communication: Signal regulatory protein family interactions
Metabolism of proteins: Surfactant metabolism
Gene Ontology:
Molecular function: protein binding; carbohydrate binding; identical protein binding
Biological process: lung alveolus development; surfactant homeostasis; defense response to bacterium; innate immune response; macrophage chemotaxis; negative regulation of interleukin-2 production; negative regulation of T cell proliferation; positive regulation of phagocytosis; reactive oxygen species metabolic process; receptor-mediated endocytosis; regulation of cytokine production
Cellular component: clathrin-coated endocytic vesicle; endocytic vesicle; endoplasmic reticulum membrane; extracellular region; lysosome; multivesicular body; cytoplasm
Genetic constraint (gnomAD): Loss-of-function variants: 14 observed, 28.08 expected, observed/expected ratio (o/e) 0.5, 90% interval 0.33 to 0.78. The upper end of that interval is the gene's LOEUF score, 0.78, which puts it in group 3 of 6, group 1 being the genes least tolerant of losing a copy. Missense variants: 388 observed, 446.15 expected, observed/expected ratio (o/e) 0.87, 90% interval 0.8 to 0.95. Synonymous variants: 145 observed, 173.38 expected, observed/expected ratio (o/e) 0.84, 90% interval 0.73 to 0.96.
Homologues: Orthologues: chimpanzee SFTPD (99% identical), macaque SFTPD (95% identical), pig SFTPD (78% identical), dog SFTPD (77% identical), rat Sftpd (75% identical), mouse Sftpd (75% identical), guinea pig SFTPD (71% identical), rabbit SFTPD (66% identical). Paralogues in human: SFTPA1 (26% identical), SFTPA2 (26% identical), COLEC11 (23% identical), COLEC10 (23% identical).
Diseases named in the same sentence as SFTPD in open-access papers:
SFTPD is named in the same sentence as 119 diseases in open-access papers, as found by Europe PMC text mining. Sharing a sentence is not in itself a finding about the gene and the disease. The quoted sentences say what the papers report.
COVID-19 (21 papers, 2020 to 2026). A disease caused by infection with severe acute respiratory syndrome coronavirus 2. "MUC5B and SFTPD are considered interesting loci associated with COVID-19 severity, and both genes are strongly correlated with pulmonary fibrosis onset." (PMID 37328761, 2023). "From the recent findings, critically ill COVID-19 patients may further develop pulmonary fibrosis, which is associated with high plasma level of surfactant protein D, a marker for epithelial damage." (PMID 41287854, 2025). "Our data suggest that SP-D is markedly elevated in severe COVID-19, consistent with prior reports that surfactant protein D is a severity indicator." (PMID 40647689, 2025). "In this study, we compared the expression of SFTPA1, SFTPA2, SFTPB, SFTPC, and SFTPD in blood among asymptomatic, mild, and severe COVID-19 patients to identify patterns related to disease severity." (PMID 40647689, 2025). "We note that our proteogenomic screen prioritised SFTPD as a candidate gene for severe COVID-19 in line with other studies, leaving the possibility of potential interactions between candidate mediators." (PMID 35970849, 2022). "Our study reveals that serum levels of interleukin (IL6), IL8, and surfactant protein-D (SP-D) can be used as early markers to stratify the severity of COVID-19, even on the day of hospitalization and before hypoxia sets in." (PMID 36518355, 2022). "Other two surfactant proteins (SFTPC and SFTPD) were expressed at remarkably low levels in the COVID-19 lungs, indicating diminished expression of all four surfactant proteins in lungs in response to SARS-CoV-2 infection." (PMID 33060566, 2020). "Although the COVID Host Genomics Initiative (throughout a GWAS meta-analysis) revealed some SNP's (in genes SFTPD, MUC5B, SLC22A31, and ACE2) involved in the susceptibility/or protection against severe COVID-19, the complete human genomic landscape of COVID-19 is incomplete." (PMID 38524554, 2024). "We not only confirmed proteins identified in previous studies, such as SFTPD which affects COVID-19 and FOXO3 which affects healthspan, notably we identified several proteins with functions involved in inflammation and immune function, apoptosis, metabolism and hormone regulation." (PMID 38575325, 2024). "In addition, SFTPD, a surfactant protein highly specific to the lung tissue was also among the overlapped proteins in predicting both COVID-19 severity groups." (PMID 37069249, 2023). "Higher levels of LCTL, SFTPD, KEL, and ATP2A3 were solely associated with a decreased risk of hospitalization (ORs = 0.86–0.93), whilst higher levels of ICAM-1 were solely associated with a decreased risk of respiratory support/death of COVID-19 (OR = 0.84)." (PMID 35239653, 2022). "This study aimed to elucidate the effect of COVID-19 on the lung’s surface tension regulatory system by examining the expression of surfactant protein genes (SFTPA1, SFTPA2, SFTPB, SFTPC, and SFTPD) across different disease severity groups." (PMID 40647689, 2025). "Moreover, another study which investigated gene expression patterns in COVID-19-affected lung tissue and SARS-CoV-2 infected cell-lines, report a downregulation of SFTPD along with several regulatory partners." (PMID 35239653, 2022). "In this preliminary study, we investigated the levels of circulating sRAGE, ANG-2, and surfactant protein D (SP-D) in serum samples of patients with COVID-19 with or without ARDS." (PMID 34001181, 2021).
pulmonary fibrosis (20 papers, 2010 to 2025). Chronic progressive interstitial lung disorder characterized by the replacement of the lung tissue by connective tissue, leading to progressive dyspnea, respiratory failure, or right heart failure. "Mutations in SFTPA1 and SFTPA2 are associated with idiopathic pulmonary fibrosis, and (along with SFTPD) play an essential role in surfactant homeostasis and in the defense against respiratory pathogens." (PMID 25961286, 2015). "Treatment with this class of drugs also resulted in a decrease in plasma surfactant protein D concentration, a reduction in the plasma levels of several chemokines implicated in lung fibrosis, and an in vitro inhibition of fibroblast profibrotic gene expression." (PMID 29952109, 2018). "Circulating content of club cell secretory protein (CCSP) and surfactant protein D (SP-D) expressed by lung epithelium were identified as biomarkers for pulmonary fibrosis induced by radiation." (PMID 36982722, 2023). "Others have reported that pneumoproteins such as surfactant protein D and Krebs von den Lungen-6 correlate with the presence of pulmonary fibrosis and alveolitis in SSc." (PMID 20813056, 2010). "Finally, a recent study found that surfactant protein D (SP-D) deficiency leads to macrophage infiltration and the production of the pro-fibrotic cytokines, TGF- β and platelet derived growth factor AA (PDGF-AA) in the BLM lung fibrosis model." (PMID 26797565, 2016).
lung carcinoma (12 papers, 2012 to 2024). "Among the lung-associated genes, SFTPB and SFTPD were highly specific to the lung, as demonstrated by the four tissue RNA samples, and they were solely found in lung cancer LM patients’ CSF." (PMID 34625644, 2021). "It is worth noting that C1q expression is reduced in lung cancer compared to the normal lung as we observed for surfactant protein D (SP-D)." (PMID 31130944, 2019). "Surfactant proteins have been extensively studied in relation to various lung diseases, and surfactant protein A2, surfactant protein B and surfactant protein D have been studied as serum lung cancer or lung disease biomarkers." (PMID 22515324, 2012). "Furthermore, we found that low expression of KCNE1, NPC2, and SFTPD promotes lung cancer cell proliferation and invasion and M2 macrophage polarization." (PMID 38509982, 2024). "PEBP4 and SFTPD have been reported as oncogenes in lung cancer." (PMID 33592039, 2021). "Moreover, SFTPD gene polymorphisms, rs721917 in particular, have been reported to correlate with susceptibility to COPD, community-acquired pneumonia, ILDs, and lung cancer." (PMID 24400879, 2014). "High expression of SFTPD might function to prevent progression of lung cancer." (PMID 34539740, 2021). "To additionally validate the accuracy of the bioinformatics analysis findings, we first examined KCNE1 in normal Epithelial cells BEAS-2B and malignant epithelial cells (lung cancer cell lines, H1299, A549, and HCC827), NPC2, and the mRNA and protein expression of SFTPD." (PMID 38509982, 2024).
chronic obstructive pulmonary disease (8 papers, 2008 to 2023). A chronic and progressive lung disorder characterized by the loss of elasticity of the bronchial tree and the air sacs, destruction of the air sacs wall, thickening of the bronchial wall, and mucous accumulation in the bronchial tree. "SFTPD encodes the surfactant protein D, and the same alternative allele was previously shown to have a negative impact on lung function and to increase the risk of chronic obstructive pulmonary disease." (PMID 37196358, 2023). "One study also found that a forest bathing trip improved pulmonary and activation-regulated chemokine, surfactant protein D, and tissue inhibitor of metalloproteinase in people with chronic obstructive pulmonary disease (COPD)." (PMID 34574854, 2021).
emphysema (8 papers, 2004 to 2025). "Further, 1400W, administered preventively in bleomycin-induced pulmonary fibrosis or curatively in surfactant protein-D deficiency-related emphysema, showed anti-nitrative, anti-inflammatory, and anti-fibrotic effects." (PMID 40298665, 2025). "Surfactant protein D has been shown to play a protective role against emphysema and other metalloproteinase‐related lung injuries." (PMID 38344410, 2024). "Circulating biomarkers such as soluble intercellular adhesion molecule (ICAM-1), surfactant protein D and soluble receptor for advanced glycation end product (sRAGE) have also been shown to be higher in more rapid emphysema progressors." (PMID 27902753, 2016). "In conclusion, compared to VCV, VV improved lung mechanics and histology as well as augmented surfactant protein-D gene expression, but increased right ventricular end-diastolic area in a rat model of elastase induced-emphysema." (PMID 27445862, 2016). "CDH13 or H cadherin is another adhesion molecule that may influence surfactant protein D levels and serum adiponectin levels, both implicated in the pathogenesis of COPD; however, CDH13 itself has not been associated with quantitative emphysema to date." (PMID 25306249, 2014).
interstitial lung disease (8 papers, 2012 to 2025). A diverse group of lung diseases that affect the lung parenchyma. "In line with this, surfactant protein-A and surfactant protein-D may be involved in smoking-related lung diseases, and cystic changes and paraseptal emphysema have been previously reported in interstitial lung disease associated with mutations in the surfactant protein-C gene." (PMID 22866751, 2012). "Serum surfactant protein D (SP-D) is a potential biomarker for the non-invasive prediction of interstitial lung disease (ILD) status." (PMID 40028331, 2025). "KL-6/MUC-1 (KL-6) and surfactant protein D (SP-D) are useful biomarkers in the diagnosis of various types of interstitial lung disease (ILD), including IPF." (PMID 22530118, 2012). "The surfactant protein-D (SP-D) has been identified as a promising biomarker to quantify epithelial damage and is elevated in patients with direct ARDS or interstitial lung diseases (ILDs)." (PMID 40160824, 2025).
lung diseases (8 papers, 2012 to 2024). "Genetic associations between polymorphisms of SFTPD and various pulmonary diseases have been reported." (PMID 33679736, 2021). "Several genetic variants have been identified for SFTPA1, SFTPA2, SFTPB, SFTPC, and SFTPD that are associated with pulmonary diseases." (PMID 33469544, 2020). "Krebs von den Lungen-6 (KL-6), CC-16, surfactant protein-A (SP-A) and surfactant protein-D (SP-D) are discussed as serological markers of pulmonary diseases." (PMID 29202744, 2017). "Changes in SFTPD secretion or degradation may potentially influence the course of CF lung disease." (PMID 33679736, 2021). "Regarding surfactant protein D and beyond, proteins that may interfere with NET formation and/or NET activities could be attractive therapeutic targets for advanced CF lung disease." (PMID 25918476, 2015).
Sepsis (8 papers, 2018 to 2024). Sepsis is defined as life-threatening organ dysfunction caused by a dysregulated host response to infection. "In Lorraine's research, the model constructed by plasma surfactant protein-D (SP-D), RAGE, IL-8, club cell secretory protein (CC-16), and IL-6 was helpful for diagnosing the occurrence of ARDS in patients with sepsis." (PMID 39319361, 2024).
idiopathic pulmonary fibrosis (7 papers, 2012 to 2024). Idiopathic pulmonary fibrosis (IPF) is a nonneoplastic pulmonary disease that is characterized by the formation of scar tissue within the lungs in the absence of any known cause. "Protein biomarkers surfactant protein D and Krebs von den Lungen-6 are markers of lung inflammation and injury not only in SSc-ILD but also in acute respiratory distress syndrome, chronic obstructive pulmonary disease, and acute exacerbation of idiopathic pulmonary fibrosis." (PMID 34374937, 2022).
acute lung injury (6 papers, 2019 to 2024). A condition of lung damage that is characterized by bilateral pulmonary infiltrates (pulmonary edema) rich in neutrophils, and in the absence of clinical heart failure. "Interleukin-6, interleukin-8, surfactant protein D, and soluble tumor necrosis factor receptor I/II (sTNFr I/II), as well as ICAM-1 and VWF, have been found to be elevated in patients with acute lung injury, and their levels fluctuate rapidly in response to different ventilation strategies." (PMID 39408067, 2024).
Obesity (5 papers, 2016 to 2022). Accumulation of substantial excess body fat. "A recent study found that obese patients have lower levels of proinflammatory cytokines (IL-6, IL-8) and surfactant protein D, The lack of reduced mortality related to obesity might be due to low grade inflammatory response." (PMID 29883469, 2018).
cystic fibrosis (4 papers, 2007 to 2022). Autosomal recessive disorder caused by pathogenic variants in the CFTR gene (cystic fibrosis transmembrane conductance regulator), which encodes a chloride and bicarbonate channel expressed in epithelial cells, and follow the diagnosis criteria. "Several studies demonstrated, that surfactant protein D (SP-D) levels are diminished in the lung of smokers or cystic fibrosis patients." (PMID 17915009, 2007). "In cystic fibrosis, the genetic contribution of the surfactant protein genes, SFTPB, SFTPC, and SFTPD are contained." (PMID 36203529, 2022).
viral infections (4 papers, 2013 to 2022). "Lung surfactant protein D (SP-D) has a protective role against various microorganisms, its deficiency being associated with increased susceptibility to bacterial or viral infections." (PMID 36293395, 2022). "Polymorphisms in the SFTPD gene are shown to be associated with increased risk of bacterial and viral infections." (PMID 33679736, 2021). "Surfactant protein D (SP-D), constitutively present in the lining fluids of the respiratory tract, plays important roles in innate host defense against virus infection." (PMID 23518578, 2013).
Allergy (3 papers, 2013 to 2018). An allergy is an immune response or reaction to substances that are usually not harmful. "Human surfactant protein D (SP-D), a member of soluble C-type lectin family called Collectins, plays a vital role in linking the innate and adaptive immunity to protect against infection, allergy, and inflammation." (PMID 29915574, 2018). "Human surfactant protein-D (SP-D), an innate immune pattern recognition soluble factor, is known to modulate a range of cytokines and chemokines, such as TNF-α and TGF-β at mucosal surfaces during infection, allergy, and inflammation." (PMID 30158928, 2018).
asthma (3 papers, 2014 to 2023). "Surfactant protein D has an important role in the pulmonary innate immune system by providing anti-inflammatory and antimicrobial activities that address chronic pulmonary diseases such as asthma, cystic fibrosis, and smoking-induced emphysema." (PMID 25538707, 2014). "We identified HMOX1, ITGAM, SFTPD and ADAM17 as the top novel targets for asthma which need to be validated experimentally whereas IL-18, TNF and VEGFA as the strongest therapeutic targets to investigate further for clinical benefit." (PMID 37735578, 2023). "HMOX1, ITGAM, DDX58, SFTPD and ADAM17 were the top novel targets identified for asthma which needs to be validated experimentally." (PMID 37735578, 2023). "Serum surfactant protein D did not demonstrate any value as a clinical biomarker of asthma." (PMID 34780682, 2022).
chronic lung disease (3 papers, 2015 to 2024). According to the definitions of the American and British Thoracic Societies, including pulmonary functional tests, X-rays, and CT scans for items such as fibrosis, bronchiectasis, bullae, emphysema, nodular or lymphomatous abnormalities. "In addition to the serum YKL-40 level, the levels of three potential biomarkers previously widely studied in chronic lung diseases, including surfactant protein D (SP-D), chemokine (C-C motif) ligand 18 (CCL18), and cancer antigen 15-3 (CA15-3), were measured." (PMID 31183362, 2019).
gestational diabetes mellitus (3 papers, 2020 to 2025). "Significantly increased leukocyte SFTPD mRNA levels were observed in hyperglycemic gestational diabetes mellitus (GDM) patients (P < 0.05) with a significant positive association with C-reactive protein." (PMID 32547959, 2020).
idiopathic interstitial pneumonia (3 papers, 2024 to 2025). A class of diffuse lung diseases that typically affect the pulmonary interstitium, although some also have a component affecting the airways (for instance, Cryptogenic organizing pneumonitis). "Plasma SPP1 levels—either alone or in combination with surfactant protein-D (SP-D) and MMP-7—have been shown to differentiate IPF from other idiopathic interstitial pneumonias (IIPs)." (PMID 40559389, 2025).